GSDMD (gasdermin D)
Diseases named in the same sentence as GSDMD in open-access papers (continued):
Sharing a sentence is not in itself a finding about the gene and the disease.
cyst (1 paper, 2022). A sac-like closed membranous structure that may be empty or contain fluid or amorphous material. "In GSDMD KO there is a robust increase in T. gondii cyst burden six weeks post infection compared to wild-type mice, indicating an inflammasome-mediated neuroinflammation requires GSDMD to control T. gondii in the brain." (PMID 35795683, 2022).
cystitis (1 paper, 2025). Inflammation of the urinary bladder. "KZMK significantly inhibited the expression of NLRP3, GSDMD, and Caspase-1 in LPS-induced cystitis, further confirming its anti-inflammatory effects." (PMID 40004227, 2025).
deafness (1 paper, 2022). An inherited or acquired condition characterized by the complete loss of the ability to hear from one or both ears. "Six types of GSDMs paralogous genes, namely GSDMA, GSDMB, GSDMC, GSDMD, and GSDME [also termed deafness, autosomal dominant 53 (DFNA5)], and pejvakin [PJVK; also termed deafness, autosomal recessive 59 9DFNB59)], have been found in humans." (PMID 36003332, 2022).
diabetic foot ulcers (1 paper, 2025). "For instance, In diabetic foot ulcers, the NET release of neutrophils in diabetic wound tissue is regulated by the NLRP3/caspase-1/GSDMD pathway, and the use of disulfiram to inhibit GSDMD can suppress this pathway, reducing NET formation and thus accelerating diabetic wound healing." (PMID 41459159, 2025).
diabetic neuropathy (1 paper, 2025). A chronic, pathological complication associated with diabetes mellitus, where nerve damages are incurred due to diabetic microvascular injury involving small blood vessels that supply these nerves, resulting in peripheral and/or autonomic nerve dysfunction. "Diabetic Neuropathy is also linked with the process of pyroptosis which requires the assembly of the inflammasome, the activation of inflammasome causes accumulation of GSDMD (Gasdermin D) caspase-1 cleaves it to produce the C- and N-gasdermin domains." (PMID 40205269, 2025).
diffuse cutaneous Leishmaniasis (1 paper, 2024). A form of LEISHMANIASIS, CUTANEOUS caused by Leishmania aethiopica in Ethiopia and Kenya, L. pifanoi in Venezuela, L. braziliensis in South America, and L. mexicana in Central America. "Furthermore, another L. mexicana strain isolated from a patient with diffuse cutaneous leishmaniasis induced similar GSDMD cleavage in neutrophils." (PMID 39250503, 2024).
encephalitis (1 paper, 2024). An acute inflammatory process affecting the brain parenchyma. "A further 3-month follow-up evaluation revealed that serum GSDMD levels in patients with anti-NMDAR encephalitis decreased significantly post-treatment, implying that GSDMD might be a potential prognostic marker." (PMID 39253076, 2024).
endometrial disorder (1 paper, 2025). A non-neoplastic or neoplastic disorder that affects the endometrium. "Given the key role of the NLRP3 inflammasome in inflammatory endometrial disorders, we investigated the expression of NLRP3 and its downstream effectors, including ASC, Caspase-1, and GSDMD, following exposure to T. pyogenes and MVs." (PMID 40691648, 2025).
endometritis (1 paper, 2022). An acute or chronic, usually bacterial infectious process affecting the endometrium. "We speculate that caspase 4 may be activated by NETs during endometritis and cleave pro-IL-1β, pro-IL-18, and GSDMD to induce pyroptosis." (PMID 36430491, 2022).
enteritis (1 paper, 2026). Inflammation of the small intestine. "Gasdermin D (GSDMD) is the only gasdermin known to protect mice against acute Salmonella enteritis." (PMID 42197534, 2026).
Erythema (1 paper, 2022). Redness of the skin, caused by hyperemia of the capillaries in the lower layers of the skin. "Patients with early-stage lesions which manifested as erythema or swelling were more likely to have cleaved GSDMD positive cells." (PMID 35396386, 2022).
gastritis (1 paper, 2025). Inflammation of the stomach. "A similar relationship was also seen for pro-GSDMD expression, and the pro-GSDMD variation between uninfected gastritis and infected gastritis expression levels was statistically significant." (PMID 40563885, 2025).
gastrointestinal infection (1 paper, 2023). "Having established that GSDMD is involved in C. rodentium-induced PCD in BMDMs but not in vivo in IECs, we proceeded evaluating its physiological effects during a C. rodentium gastrointestinal infection." (PMID 37080966, 2023).
Giardia infection (1 paper, 2021). "To identify the mediators leading to Giardia infection-associated GSDMD cleavage, we used N-acetylcysteine (NAC) and Ac-YVAD-CMK (AYC) to inhibit ROS generation and CASP1 activation, respectively." (PMID 34943932, 2021). "In the present study, we confirmed the involvement of A20-mediated NLRP3 deubiquitination in inflammasome activation, CASP1 and GSDMD cleavage, and IL-1β and IL-18 release during Giardia infection." (PMID 34943932, 2021).
Glucose intolerance (1 paper, 2022). Glucose intolerance (GI) can be defined as dysglycemia that comprises both prediabetes and diabetes. "Moreover, GSDMD deficiency causes a mild increase in glucose intolerance and adiposity when challenged with a HFD, partly by regulating the expression of peroxisome proliferator-activated receptor gamma (PPARγ)." (PMID 36065376, 2022). "Compared with the WT HFD mice, GSDMD KO HFD mice exhibited a mild increase in HFD-induced glucose intolerance with increased systemic and adipose tissue IL-1β levels." (PMID 36065376, 2022). "Considering that the lack of GSDMD did not abrogate HFD-induced adipose tissue inflammation, it is not surprising that glucose intolerance was not reduced in GSDMD KO mice relative to WT mice." (PMID 36065376, 2022).
graft versus host disease (1 paper, 2022). An immune system disorder that occurs after allogeneic hematopoietic stem cell transplant and is a reaction of donor immune cells against host tissues. "Caspase-11/GSDMD-triggered pyroptosis also contributed to acute graft-versus-host disease-related intestinal injury in allogeneic hematopoietic stem cell transplantation, while deletion of caspase-11 or GSDMD relieved intestinal inflammation." (PMID 36505474, 2022).
H1N1 virus infection (1 paper, 2025). "H1N1 virus infection dose- and time dependently induced GSDMD and GSDME cleavage in these two cell lines, which generated a truncated N-terminal fragment with a molecular mass around 30 and 34 kDa, respectively." (PMID 39811662, 2025).
hearing loss (1 paper, 2025). "Our findings uncover a central role for SCs in noise-induced hearing loss and identify GSDMD-mediated intercellular communication as a potential therapeutic target." (PMID 41407982, 2025).
hematoma (1 paper, 2022). A hematoma is a collection of blood from a vascular structure into an extravascular space. "The number of GSDMD-positive microglia in the peri-hematoma tissue was decreased at 24 h after ICH in the ICH+Locostatin+VX-765 group compared with the ICH+Locostatin group." (PMID 35154128, 2022).
hepatic granuloma (1 paper, 2020). A granuloma located in the liver. "For this reason, we decided to evaluate whether other inflammasome pathway-related molecules, such as Casp-1, GSDMD, and IL-1R, played a role in the formation of hepatic granuloma." (PMID 32431709, 2020).
hyperandrogenism (1 paper, 2025). Excessive secretion of androgens from the adrenal glands or gonads. "Hyperandrogenism stimulates chronic low-grade inflammation in the ovary and induces pyroptosis through GSDMD cleavage." (PMID 40830889, 2025).
hypothyroidism (1 paper, 2023). Abnormally low levels of thyroid hormone. "Treatment with Kp10 suppressed the increase in NLRP3/Nlrp3, IL-1β, Il18, and Gasdermin D/Gsmd caused by hypothyroidism at the maternal-fetal interface." (PMID 37047793, 2023).
Impaired glucose tolerance (1 paper, 2023). An abnormal resistance to glucose, i.e., a reduction in the ability to maintain glucose levels in the blood stream within normal limits following oral or intravenous administration of glucose. "The key pyroptotic protein defect in muscular dystrophy mice alleviates atrophy and improves muscle function, and the inhibition of Caspase1/GSDMD/IL-1β pathways ameliorates skeletal muscle pathology in rats with impaired glucose tolerance induced by a high-fat diet." (PMID 37720530, 2023).
intestinal inflammation (1 paper, 2025). "Gasdermin D (GSDMD)-mediated release of IL-1β-containing exosomes is involved in the pathogenesis of intestinal inflammation." (PMID 40659888, 2025).
invasive ductal carcinoma (1 paper, 2024). "In five patients with invasive ductal carcinoma, we found expression of GSDMD in tumor cells as well as in immune cells and endothelial cells." (PMID 39224600, 2024).
kidney tumors (1 paper, 2022). "Thus, we hypothesized that GSDMD may trigger the release of inflammatory factors and induce potential interactions with other immune responses, thereby promoting the invasiveness of kidney tumors." (PMID 36003332, 2022).
Krabbe disease (1 paper, 2023). A lysosomal disorder that affects the white matter of the central and peripheral nervous systems. "On the basis of these and findings by others, we hypothesized that inflammasome activation and GSDMD-mediated pyroptosis might occur in Krabbe disease and contribute substantially to pathogenesis and neurological disability." (PMID 36519759, 2023).
leishmaniasis (1 paper, 2023). Infectious disease that is transmitted through the bite of hematophagous female phlebotomine sand flies. "In this study, we reveal that GSDMD is activated in BMDMs and in lesions from patients with Leishmaniasis." (PMID 36828815, 2023). "Altogether, our findings reveal that Leishmania subverts the normal functions of GSDMD, an important molecule to promote inflammasome activation and immunity in Leishmaniasis." (PMID 36828815, 2023). "Importantly, our experiments with clinical samples demonstrated activation of the inflammasome and GSDMD in the lesions of Leishmaniasis patients, supporting our assertion of the importance of GSDMD and inflammasomes in the course of the disease." (PMID 36828815, 2023). "We demonstrate that GSDMD is critical in the immunity to Leishmaniasis." (PMID 36828815, 2023). "To assess inflammasome activation in skin biopsies of Leishmaniasis patients, we stained the patient tissues with anti-ASC, anti-NLRP3, and cleaved GSDMD (N-terminal)." (PMID 36828815, 2023). "Gasdermin-D is cleaved into a noncanonical fragment, indicating that Leishmania subverts Gasdermin-D-mediated host response to establish leishmaniasis." (PMID 36828815, 2023).
Lewis lung carcinoma (1 paper, 2021). "When activated OT-1 T cells were co-cultured with ovalbumin-expressing Lewis lung carcinoma (3LL-OVA) cells, the co-localization of GSDMD and GzmB was observed in the CTLs near their immune synapses; moreover, CTL cytotoxicity towards 3LL-OVA cells was diminished following GSDMD knockdown." (PMID 34429144, 2021).
localized scleroderma (1 paper, 2022). Localized scleroderma is the skin localized form of scleroderma characterized by fibrosis of the skin causing cutaneous plaques or strips. "Next, to explore what kind of cells have cleaved GSDMD in scleroderma skin, we downloaded and analyzed the GSE160536 data set, which included single-cell RNA sequencing (scRNA-seq) data from the skin lesions of six localized scleroderma patients." (PMID 35396386, 2022).
lymphopenia (1 paper, 2022). Reduction in the number of lymphocytes. "In line with this, the pyroptotic marker, GSDMD, showed a positive correlation with BK1-8, suggesting an implication of KKS in lymphopenia." (PMID 35812405, 2022).
malignant mesothelioma (1 paper, 2024). A malignant neoplasm of the pleura or peritoneum, arising from mesothelial cells. "Two chemotherapeutics (doxorubicin and cisplatin) can activate the NLRP3‒GSDMD pyroptosis axis to exert antitumour effects in malignant mesothelioma." (PMID 38804602, 2024).
meningioma (1 paper, 2026). A generally slow growing tumor attached to the dura mater. "Treatment of diverse patient meningiomas ex vivo with 8803 induces direct tumor cytotoxicity through inflammatory cell death pathways, including induction of gasdermin D membrane pore formation." (PMID 41680157, 2026).
monocytic leukemia (1 paper, 2025). "For example, inhibiting palmitoylation of human GSDMD at the C191 site using the specific inhibitor NU 6300 effectively suppressed GSDMD cleavage in the human monocytic leukemia cell lines." (PMID 40832584, 2025).
mucinous stomach adenocarcinoma (1 paper, 2022). "GSDMC and GSDMD mutations were more likely associated with mucinous stomach adenocarcinoma." (PMID 35164740, 2022).
muscular atrophy (1 paper, 2023). The loss of muscle tissue due to inactivity or disease. "Interestingly, GSDMD-mediated pyroptosis is associated with glucocorticoid-induced muscular atrophy via various mechanisms, which is in clear contrast to the clinical observation that glucocorticoids are beneficial in DMD patients." (PMID 37239853, 2023).
myeloma (1 paper, 2020). "Thus, inflammasome/pyroptosomes activation and cleavage of GSDMD and PANX1 are likely to induce pore formation leading to the “ballooning” morphology and the subsequent release of LDH and IL-1b seen in the drug treated myeloma cells." (PMID 33066043, 2020).
nephrocalcinosis (1 paper, 2025). Nephrocalcinosis is a disorder that occurs when too much calcium is deposited in the kidneys. "In order to distinguish direct from indirect effects of GSDMD on nephrocalcinosis, we investigated whether Gsdmd deficiency affects the formation of CaOx crystals in urine by supersaturating calcium and oxalate in urine samples from each mouse genotype." (PMID 40221396, 2025). "To explore the possibility of a functional role of GSDMD in nephrocalcinosis-related kidney injury, we fed WT and Gsdmd−/− mice an oxalate-rich, calcium-depleted diet to induce progressive oxalate nephropathy." (PMID 40221396, 2025).
nephrotic syndrome (1 paper, 2024). A collection of symptoms that include severe edema, proteinuria, and hypoalbuminemia; it is indicative of renal dysfunction. "The expression of NLRP3, Casapase-1, GSDMD, IL-1β, and α-SMA in the renal tissue of nephrotic syndrome rats increased, E-cadherin decreased, and Tunel staining showed that an increase of renal tubular epithelial cells with broken nuclei." (PMID 38995910, 2024).
ocular hypertension (1 paper, 2021). Abnormally high intraocular pressure. "To understand the underlying mechanism of PM2.5-related ocular hypertension, we measured the levels of proteins associated with the classic pyroptosis pathway (NLRP3/caspase-1/IL-1β/GSDMD) in aqueous humor outflow tissue." (PMID 33663554, 2021).
orchitis (1 paper, 2024). Inflammation of one or both testes due to viral or bacterial infections. "Altogether, these data indicated that GSDMD deficiency in macrophages impaired the T-cell response by negatively regulating antigen presentation, thereby controlling orchitis." (PMID 38177538, 2024). "Overall, our findings highlight GSDMD as a potential therapeutic target for the treatment of UPEC-induced orchitis." (PMID 38177538, 2024). "The use of GSDMD inhibitors demonstrated protective effects in mice subjected to UPEC-induced orchitis." (PMID 38177538, 2024). "In testicular macrophages, GSDMD promoted inflammation and antigen presentation, thereby enhancing the T-cell response after orchitis." (PMID 38177538, 2024). "We found that Gasdermin D (GSDMD) is activated during uropathogenic Escherichia coli (UPEC)-induced orchitis." (PMID 38177538, 2024). "To further elucidate the mechanism via which GSDMD in macrophages promoted orchitis, we performed RNA-sequencing (RNA-seq) of macrophages (CD45+CD11b+Ly6G−F4/80+) sorted from the testes of WT and Gsdmd−/− mice treated with UPEC (Fig. EV4A)." (PMID 38177538, 2024). "Administration of GSDMD inhibitors conferred protection against UPEC infection-induced orchitis (Fig. EV5)." (PMID 38177538, 2024). "Thereafter, we comprehensively examined the effects of GSDMD on the testes in the context of UPEC-induced orchitis." (PMID 38177538, 2024). "Our study demonstrates the role of GSDMD in driving orchitis." (PMID 38177538, 2024). "Overall, these data suggested that the inhibition of GSDMD-mediated pyroptosis can control UPEC-induced orchitis and indicated that GSDMD might be a potential therapeutic target for UPEC-induced acute orchitis." (PMID 38177538, 2024). "In addition, we showed that GSDMD-induced pyroptosis in macrophages enhanced antigen presentation, thereby amplifying T-cell immune responses during orchitis." (PMID 38177538, 2024). "Collectively, these findings provide the first demonstration of GSDMD’s role in driving orchitis and suggest that GSDMD may be a potential therapeutic target for treating orchitis." (PMID 38177538, 2024). "In summary, we have demonstrated that GSDMD is activated during UPEC-induced orchitis." (PMID 38177538, 2024). "Taken together, these data suggested that GSDMD is essential for the pathogenesis of orchitis." (PMID 38177538, 2024). "However, whether the role of GSDMD in regulating antigen presentation can be attributed to the promotion of S100A8 expression and how GSDMD enhances S100A8 expression during orchitis requires further investigation." (PMID 38177538, 2024). "Consistent with this, we found that GSDMD, the key executioner of pyroptosis downstream of inflammasomes, contributes to UPEC-induced orchitis." (PMID 38177538, 2024). "However, the pathophysiological function of GSDMD in orchitis remains largely unknown." (PMID 38177538, 2024). "Uropathogenic Escherichia coli (UPEC)-induced orchitis and experimental autoimmune orchitis (EAO) mouse models were used to identify the critical role of the Gasdermin D (GSDMD)-mediated pyroptosis in the pathogenesis of orchitis." (PMID 38177538, 2024). "Furthermore, immunofluorescence analysis showed that GSDMD was upregulated and mainly co-localized with F4/80+ macrophages in the interstitial spaces after UPEC infection, indicating that GSDMD in testicular macrophages might be responsible for promoting UPEC-induced orchitis." (PMID 38177538, 2024). "To further confirm the role of GSDMD-mediated pyroptosis in orchitis and the interventional effect of targeted inhibition of GSDMD activation in UPEC-induced orchitis, we administered DMF to mice with UPEC-induced orchitis." (PMID 38177538, 2024).
osteomyelitis (1 paper, 2021). An acute or chronic inflammation of the bone and its structures due to infection with pyogenic bacteria. "The expressions of pyroptosis-related proteins, NLRP3, caspase-1, and GSDMD were significantly increased in mouse osteomyelitis model induced by Staphylococcus aureus and infectious bone fragments of patients with osteomyelitis." (PMID 33215255, 2021).
pemphigus (1 paper, 2025). Pemphigus is a group of rare autoimmune diseases that cause blistering of the skin and mucous membranes (mouth, nose, throat, eyes, and genitals).This conditioncan occur at any age, but often strikes people in middle or older age. "This includes the significance of Gasdermin D, the key pyroptosis protein, being expressed in pemphigus and the mechanism by which pyroptosis-related molecules activate pyroptosis through a particular signaling pathway." (PMID 40102153, 2025).
pituitary adenoma (1 paper, 2026). "The Escherichia coli are phagocytosed by the microglial cells in the pituitary gland, then activate GSDMD protein releasing HMGB1, and promote the tumorigenesis of pituitary adenoma by activating the MAPK pathway." (PMID 41655211, 2026).
Pleural effusion (1 paper, 2023). The presence of an excessive amount of fluid in the pleural cavity. "However, GSDMD concentrations have shown promise in differentiating various types of pleural effusion with high sensitivity and specificity, including exudative, transudative, tuberculous, malignant, and parapneumonic effusions." (PMID 38002346, 2023).